CCL27 (C-C motif chemokine ligand 27)
Diseases named in the same sentence as CCL27 in open-access papers (continued):
Sharing a sentence is not in itself a finding about the gene and the disease.
myeloma (7 papers, 2016 to 2025). "Beside already known myeloma-associated chemotactic molecules, CCL27 was overexpressed in patients' samples." (PMID 27732933, 2016). "Multiple myeloma plasma cell expresses high CCR10 and CCL27 levels in bone marrow, associated with poor prognosis and drug resistance." (PMID 41050670, 2025). "ChIP-on-chip data revealed that heparanase bound to regulatory regions of myeloma-related genes (i.e., CXCL12), encodes for SDF-1, CXCR4, CXCL2, CXCR3, CCL27, CX3CL1, and LCN2." (PMID 36980254, 2023). "The specific rescue from bortezomib-induced cell death by CCL27 led us to further investigate the proteasomal activity of myeloma cells under treatment." (PMID 27732933, 2016). "Out of them, one factor was significantly regulated in myeloma-stroma cell coculture treated with bortezomib +/− CCL27, i.e. IL-10." (PMID 27732933, 2016). "In summary, we found that CCL27, a novel chemokine in the context of the bone marrow microenvironment, confers myeloma drug resistance to proteasome inhibitors by binding to stromal CCR10 and inducing IL-10, a myeloma survival factor." (PMID 27732933, 2016). "As shown, addition of CCL27 rescued myeloma cells efficiently from treatment in this setting (pictures and graph)." (PMID 27732933, 2016). "Primary stroma cells isolated from three myeloma patients also rescued myeloma cell lines, and survival of CD138-sorted primary myeloma cells from four patients seeded on HS-5 layer and treated with bortezomib was ameliorated by the addition of CCL27." (PMID 27732933, 2016). "Since CCL27 is primarily known for its T cell attracting properties, we additionally investigated a possible correlation between infiltrating T cells and CCL27 levels in myeloma patients on the basis of CD62L/CD45RA expression." (PMID 27732933, 2016). "In the presence of HS-5 stroma cells, the addition of CCL27 rescued myeloma cells almost completely from bortezomib-induced cell death." (PMID 27732933, 2016). "Here, we discovered that a single chemokine, CCL27, which is upregulated in myeloma patients, induced bortezomib resistance in myeloma cells." (PMID 27732933, 2016). "Since NF-κB constitutes also a major survival pathway of myeloma cells and their microenvironment in general, this counterregulation by CCL27 warrants further detailed investigations." (PMID 27732933, 2016). "CAR-T cells targeting CCR10 in a CCL27-dependent manner eliminate myeloma cells in vitro." (PMID 41050670, 2025). "It has been shown that CCL27 triggers resistance in myeloma cells." (PMID 30214382, 2018). "From our data we suggest that blocking the CCR10/CCL27/IL-10 myeloma-stroma crosstalk is a novel therapeutic target that could be especially relevant in early refractory myeloma patients." (PMID 27732933, 2016). "We also detected CCL27 in the supernatants from myeloma cell lines as well as stroma cells." (PMID 27732933, 2016). "Here we investigated bone marrow-derived chemokines of naive and therapy-refractory myeloma patients and discovered that high levels of the chemokine CCL27, known so far for its role in skin inflammatory processes, correlated with worse overall survival of the patients." (PMID 27732933, 2016). "In vitro as well as in an in vivo model we could show that CCL27 triggers bortezomib-resistance of myeloma cells." (PMID 27732933, 2016). "Importantly, many other cell types are involved in the microenvironmental crosstalk in myeloma with some of them (e.g. specific subtypes of T cells and dendritic cells) also being responsive to CCL27." (PMID 27732933, 2016). "In summary, we suggest that targeting the CCR10/CCL27 crosstalk in the myeloma microenvironment could contribute to the development of tailored therapeutic interventions bringing multiple myeloma to a chronic, manageable disease or even to cure." (PMID 27732933, 2016).
myeloma (continued). "Therefore, in the patient setting, the selection of high producer myeloma cell clones and/or the observed upregulation of CCL27 in myeloma cells upon bortezomib-treatment could tip the balance in favour of the tumor." (PMID 27732933, 2016). "On the cellular therapy frontier, structure-guided CCL27-based CAR T cells targeting CCR10-expressing tumor cells, such as in multiple myeloma, have been described as promising candidates in early proof-of-concept." (PMID 41050670, 2025). "On the other hand, bortezomib treatment led to enhanced CCL27 expression in myeloma cell lines, but not in HS-5 stroma cells." (PMID 27732933, 2016). "Whereas CCL27 rescued myeloma cells from drug-treatment, addition of CCL28 had no impact on cell survival in both assays." (PMID 27732933, 2016). "Concomitantly, surface expression of monoclonal immunoglobulin was decreased on IL-10 treated myeloma cells (NCI-H929, IgA myeloma; OPM-2, IgG myeloma), whereas we found higher levels of free immunoglobulin in the supernatants of these cells upon CCL27 +/− bortezomib treatment." (PMID 27732933, 2016). "In line with this, we found that CCL27 levels in the range of healthy donors (up to 3000 pg/ml) could not protect myeloma cells from bortezomib-induced cell death in vitro." (PMID 27732933, 2016). "However, CCL27 did not induce NF-κB activity in myeloma cell lines (data not shown)." (PMID 27732933, 2016).
asthma (5 papers, 2012 to 2022). "This list included many genes with a purported role in regulation of the immune response in asthma: interleukins (IL2IL27 and IL33), chemokines (CXCL1CXCL17CCL5 and CCL27), mucins (MUC2MUC13 and MUCL1), TLR7 and NOS2, among others." (PMID 22713245, 2012).
lung carcinoma (5 papers, 2022 to 2024). "A recent MR analysis demonstrated that C-C motif chemokine 27 (CCL27) levels in circulation are positively associated with the risk of lung cancer, whereas interleukin-18 levels are inversely associated with such risk." (PMID 38755605, 2024). "In a recent comprehensive study, we expanded upon previous single-item MR findings that linked CCL27/CTACK positively with lung cancer incidence in non-smokers, and IL-18 negatively with lung cancer and lung adenocarcinoma rates." (PMID 39132165, 2024). "Cochrane’s Q test did not provide evidence of heterogeneity between CCL14 (p = 0.916), CCL19 (p = 0.446), CCL20 (p = 0.130), CCL21 (p = 0.878), CCL27 (p = 0.762), CXCL9 (p = 0.340) and CXCL13 (p = 0.770) and lung cancer." (PMID 38075694, 2023).
multiple sclerosis (5 papers, 2015 to 2024). A progressive autoimmune disorder affecting the central nervous system resulting in demyelination. "Upregulation of serum CCL27, as an inflammatory chemokine associated with the homing of memory T cells to sites of inflammation, has recently been identified as an indicator for multiple sclerosis." (PMID 33806460, 2021). "CCL27 induces the homing of memory T cells to sites of inflammation and has been found by others to be elevated in the serum of people with multiple sclerosis." (PMID 38368354, 2024). "More recently, elevated CCL27 levels in patients with multiple sclerosis was observed." (PMID 30214382, 2018).
skin inflammation (5 papers, 2021 to 2025). "The CCR10/CCL27 interaction mediates the recruitment of memory T cells to the skin and regulates the induction of antigen-specific skin inflammation in vivo." (PMID 40040698, 2025). "At the same time, systemic administration of anti-CCR4 ligand (CCL17 and CCL22) and CCR10 ligand (CCL27) comprehensive antibody can significantly inhibit T cell migration and skin inflammation." (PMID 40040698, 2025). "In a mouse model of AD, topical melatonin treatment improved gross dermatitis severity, reduced epidermal hyperplasia and lymphocyte infiltration in the skin, and decreased IP-10, CCL27, IL-4, and IL-17 levels in superficial skin-draining lymph nodes." (PMID 35163297, 2022). "For example, CCR10/CCL27 interactions were proven to alleviate skin inflammation via regulating T cells." (PMID 34831296, 2021). "In vivo, homing assay, functional blockade of CCL27 by anti-CCL27 monoclonal antibody prevented CCR4-deficient T cells from migrating to the site of skin inflammation but not in wild-type mice." (PMID 40040698, 2025). "We found that in DNCB-stimulated Balb/c mice, topical melatonin treatment improved gross dermatitis severity, reduced epidermal hyperplasia and lymphocyte infiltration in the skin, and decreased IP-10, CCL27, IL-4, and IL-17 levels in superficial skin-draining lymph nodes." (PMID 35163297, 2022). "From our current study, topical melatonin treatment improved the skin inflammation and thickening in a mouse model of AD, which is potentially due to regulation of inflammatory cytokines and chemokines including IP-10, MCP-1, CCL-27, and IL-4, and reduction of cytokine-induced cell proliferation." (PMID 35163297, 2022).
Anxiety (4 papers, 2012 to 2023). Intense feelings of nervousness, tension, or panic often arise in response to interpersonal stresses. "Low CCL27 serum concentrations have previously been associated with higher anxiety scale scores, which is a risk factor for suicide." (PMID 35697758, 2022).
colorectal cancer (4 papers, 2016 to 2024). A primary or metastatic malignant neoplasm that affects the colon or rectum. "In addition, six homeostatic chemokines, CXCL12, CCL1, CCL20, CCL25, CCL27, and CXCL11, were upregulated in the peripheral blood of patients with advanced colorectal cancer, which has also been reported to be associated with tumor progression." (PMID 37063892, 2023).
Pruritus (4 papers, 2016 to 2025). Pruritus is an itch or a sensation that makes a person want to scratch. "In group 1, compared with group 2, HDM-induced IL-31 in CLA+ T cells positively correlated with patient ́s pruritus intensity, and plasma levels of CCL27 and periostin." (PMID 36993985, 2023). "A correlation between IL-31 production and patient’s pruritus intensity, plasma CCL27 and periostin was detected." (PMID 36993985, 2023). "Within group 1 of patients, HDM-induced IL-31 response directly correlated with pruritus (r = 0.67, p = .0036) and plasma levels of CCL27 (r = 0.62, p = .0090) and periostin (r = 0.56, p = .050)." (PMID 36993985, 2023).
skin cancer (4 papers, 2013 to 2022). "Furthermore, our GWEA results are in agreement with previous reports that CCL27 is downregulated through activation of the RAS-MAPK-signaling pathway in human skin tumors." (PMID 23379751, 2013). "Similarly, higher incidence of skin cancer seen in organ transplantation may be related to high levels of CCL27." (PMID 30214382, 2018). "When exposed to UV radiation, stressed mice had a shorter time to form skin tumors and showed lower IFN-γ, CCL27/CTACK expression levels and fewer CD4+ infiltrating cells than control group." (PMID 36275706, 2022).
endometriosis (3 papers, 2018 to 2024). The growth of functional endometrial tissue in anatomic sites outside the uterine body. "Although we found potential importance of the ratio TNFα/CCL27 for separating patients with minimal/mild endometriosis from the control group of patients, the accuracy achieved by the algorithm was insufficient." (PMID 31723213, 2019). "Except for TNFα/CCL27 protein ratio that has been consistently reported by the random forest algorithm as the most valuable feature for separating patients with minimal/mild endometriosis from controls." (PMID 31723213, 2019).
nasopharyngeal carcinoma (3 papers, 2018 to 2021). A carcinoma arising from the nasopharyngeal epithelium. "CCL27 was once regarded as a sensitive serum biomarker to distinguish nasopharyngeal carcinoma patients from healthy donors (highly expressed in abnormal populations due to the activated immune system)." (PMID 34179092, 2021). "Likewise, CCL27 is found in normal nasopharyngeal tissue samples particularly those individuals with seropositive Epstein- Bar virus capsid antigen- specific IgA level (VCA-IgA- positive) and is suggested as a plasma novel biomarker for nasopharyngeal carcinoma." (PMID 30214382, 2018).
prostate carcinoma (3 papers, 2022 to 2023). A carcinoma that arises from epithelial cells of the prostate gland. "CCL24 was a risk factor for prostate cancer, and CCL27 was a risk factor for non-small cell lung cancer." (PMID 38075694, 2023). "In contrast, race-specific differences were observed for significantly higher serum levels of CXCL2 (p < 0.0001), CXCL5 (p = 0.016), and IL-6 (p = 0.004), and lower levels of CCL23 (p < 0.0001) and CCL27 (p = 0.016) in AA prostate cancer patients (n = 14) compared to CA (n = 14)." (PMID 37698493, 2023).
Stroke (3 papers, 2024 to 2025). Sudden impairment of blood flow to a part of the brain due to occlusion or rupture of an artery to the brain. "In the unstimulated saliva of stroke patients, we demonstrated significantly higher levels of chemotactic factors (CTACK/CCL27, IL-8/CXCL8, MIG/CXCL9, MIF) and growth factors (basic FGF, G-CSF, HGF, LIF, VEGF) compared to controls." (PMID 40221607, 2025). "Using MR, we identified 2 proteins with an effect on subsequent MACE after a stroke: CCL27 (effect OR= 0.77, 95% CI = 0.66-0.88, adj." (PMID 38352469, 2024). "We observed 2 proteins (CCL27 and TNFRSF14) associated with subsequent stroke events that have a role in inflammation." (PMID 39038097, 2024). "We observed putatively causal evidence for 2 novel proteins (CCL27 and TNFRS14) associated with subsequent MACE risk in pQTL, suggesting that inflammation is a contributing factor to subsequent MACE outcomes after incident stroke AIS." (PMID 39038097, 2024).
urticaria (3 papers, 2016 to 2022). A vascular reaction of the skin characterized by erythema and wheal formation due to localized increase of vascular permeability. "CCL11, CCL17, CCL26, and CCL27 are implicated in the pathogenesis of urticaria." (PMID 27057079, 2016). "In our study, serum levels of CCL11, CCL17, CCL26, and CCL27 increased significantly in both AU and CSU patients, indicating that elevated CCL11, CCL17, CCL26, and CCL27 are involved in the pathogenesis of urticaria." (PMID 27057079, 2016). "Among chemokines, CCL26 and CCL27 showed higher AUC (0.907 versus 0.906) values, providing maximum efficiency in prediction of moderate-to-severe urticaria with a sensitivity of 75.0% and 78.8% and specificity of 95% and 90.0%, respectively." (PMID 27057079, 2016). "For example, CCL27 (CTAK) is secreted in the skin and seems to be associated with urticaria." (PMID 35202004, 2022). "Moreover, CCL26 and CCL27 showed a high AUC, providing maximum efficiency in prediction of moderate-to-severe urticaria with high sensitivity and specificity." (PMID 27057079, 2016). "Positive associations were found between D-dimer and CCL27, CCL17, and CCL26 in our study, indicating that D-dimer and chemokine might play a concomitant role in the pathogenesis of urticaria." (PMID 27057079, 2016).
allergic reactions (2 papers, 2023 to 2024). "Together we report both the coagulation cascade, specifically the genes F13A1, SERPINE1 and C1R, and the CCR10/CCL27 axis, as candidate pathways used by IgE-binding monocytes in the mechanism of allergy." (PMID 37193769, 2023).
Alzheimer disease (2 papers, 2022 to 2023). A progressive, neurodegenerative disease characterized by loss of function and death of nerve cells in several areas of the brain leading to loss of cognitive function such as memory and language. "Evidence suggest that 1 standard deviation (SD) increase in levels of CTACK (CCL27) (OR = 1.09 95%CI: 1.01 to 1.19, p = 0.03) increased risk of Alzheimer’s disease." (PMID 35580794, 2022). "Exception was CTACK (CCL27), where we observed evidence of a causal effect on Alzheimer’s disease (IVW: OR per 1 standard deviation (SD) increase = 1.09 95% CI: 1.01 to 1.19, p = 0.03)." (PMID 35580794, 2022). "We observed some evidence for a detrimental effect of greater levels of CTACK (CCL27), MIP-1b (CCL4), Eotaxin, GROa (CXCL1), MIG (CXCL9), IL-8 and IL-2 on the risk of Alzheimer’s disease." (PMID 35580794, 2022). "However, future research is required to better characterise the role of CTACK (CCL27) in Alzheimer’s disease aetiology." (PMID 35580794, 2022). "More specifically, CTACK (CCL27) is a chemokine involved in the CNS as it is expressed in the cerebral cortex and limbic regions which are mainly affected in Alzheimer’s disease." (PMID 35580794, 2022).
endometrial cancer (2 papers, 2019 to 2022). Primary or metastatic malignant neoplasm involving the endometrium (mucous membrane that lines the endometrial cavity). "CCL27, is also a NK cell chemoattractant molecule, and is, in endometrial cancer, less produced in the tumor compared to the healthy adjacent tissue." (PMID 31105699, 2019).
glioma (2 papers, 2014 to 2021). A benign or malignant brain and spinal cord tumor that arises from glial cells (astrocytes, oligodendrocytes, ependymal cells). "In previous studies, the molecular mechanisms of HTR1A, CCL13, CCL21, and CCL27 in gliomas remained unclear." (PMID 33503296, 2021). "After administration of CCL27 to glioma cells, we observed a strong increase in p-Akt." (PMID 25149529, 2014). "Exogenous CCL27 stimulation increased the invasion of glioma cells compared with control." (PMID 25149529, 2014). "Treatment of CCR10 siRNA also suppressed the proliferation of glioma in the presence of CCL27." (PMID 25149529, 2014). "After mechanism validation both in vitro and in vivo, we demonstrated that p-Akt was key downstream signal involved in CCL27/CCR10 mediated proliferation and invasion of glioma." (PMID 25149529, 2014). "To assess effects of CCL27 on glioma cells, we stimulated U87 and LN229 cells with recombinant human chemokine CCL27 under serum deprivation conditions and examed cell proliferation by cell count and MTT assay." (PMID 25149529, 2014). "Therefore, p-Akt was involved in CCL27/CCR10 mediated proliferation and invasion of glioma in vitro." (PMID 25149529, 2014). "CXCL10, CCL13, SAA1, and CCL27 were more highly expressed in elderly, high‐grade, 1p19q non‐codel, IDH‐wildtype glioma patients, while SSTR5, CCL21, and HTR1A expressions were low in these malignant clinicopathological features of gliomas." (PMID 33503296, 2021).
keloid (2 papers, 2018 to 2019). An irregularly shaped, elevated mark on the skin caused by deposits of excessive amounts of collagen during wound healing. "We also examined secretion of a previously established wound healing mediator panel (CCL2, IL-6, CXCL8, VEGF, HGF and CCL27), which showed reduced HGF secretion in the reconstructed keloid model compared to the normal skin model." (PMID 31187196, 2019).
Obesity (2 papers, 2018 to 2023). Accumulation of substantial excess body fat. "Other cytokines in the clusters have not previously been associated with T2D or human obesity, such as CCL27/CTACK." (PMID 29738558, 2018). "In humans, cytokine profiles in the blood can be reversed after bariatric surgery—elevated CCL14, soluble vascular endothelial growth factor receptor 2 (VEGFR2), and platelet-derived growth factor BB in obesity are reduced, and lower CXCL12, CCL11, and CCL27 in obesity are increased." (PMID 38037591, 2023).
ovarian carcinoma (2 papers, 2016 to 2022). A malignant neoplasm originating from the surface ovarian epithelium. "Similarly, transfecting CCL27 into ovarian carcinoma cells resulted in reduced tumor growth by antitumor immune responses." (PMID 27807435, 2016).
anaphylaxis (1 paper, 2022). An acute hypersensitivity reaction that occurs from exposure to an allergen. "Although skin symptoms were highly prevalent during anaphylaxis in our cohort, there were only a few samples with an increase in CCL27 in serum." (PMID 35202004, 2022).
Candida infection (1 paper, 2012). "Of the chemoattractant mediators, several chemokines (Ccl25, Ccl27, Ccl28) and chemokine receptors (Ccr9, Ccr10, Cxcr5, Cxcr6, Cxcr7) associated with adaptive immunity were not induced after Candida infection." (PMID 22916017, 2012).